CCDC178 (coiled-coil domain containing 178)
Description:
May play a crucial role in head shaping and sperm flagellum formation.
Synonyms: C18orf34; FLJ44050
Tractability: PROTAC: ubiquitination databases record sites on it.
Gene: Protein-coding gene on chromosome 18 (32,937,402 to 33,441,101, reverse strand). Ensembl gene ENSG00000166960.
Subcellular location: Cytoplasm, cytoskeleton, microtubule organizing center, centrosome
Gene Ontology:
Biological process: spermatid development; manchette assembly
Cellular component: ciliary basal body; centrosome
Genetic constraint (gnomAD): Loss-of-function variants: 40 observed, 38.66 expected, observed/expected ratio (o/e) 1.03, 90% interval 0.8 to 1.35. The upper end of that interval is the gene's LOEUF score, 1.35, which puts it in group 5 of 6, group 1 being the genes least tolerant of losing a copy. Missense variants: 420 observed, 405.93 expected, observed/expected ratio (o/e) 1.03, 90% interval 0.95 to 1.12. Synonymous variants: 116 observed, 131.73 expected, observed/expected ratio (o/e) 0.88, 90% interval 0.76 to 1.03.
Homologues: Orthologues: chimpanzee CCDC178 (98% identical), macaque CCDC178 (91% identical), rabbit CCDC178 (63% identical), dog CCDC178 (61% identical), pig CCDC178 (60% identical), rat Ccdc178 (51% identical), mouse Ccdc178 (50% identical).
Diseases named in the same sentence as CCDC178 in open-access papers:
CCDC178 is named in the same sentence as 14 diseases in open-access papers, as found by Europe PMC text mining. Sharing a sentence is not in itself a finding about the gene and the disease. The quoted sentences say what the papers report.
gastric cancer (4 papers, 2015 to 2023). A primary or metastatic malignant neoplasm involving the stomach. "The coiled-coil domain-containing protein 178 (CCDC178) is an 867 amino acid polypeptide that is mutated in several human cancers including gastric cancer and HCC." (PMID 33854965, 2021). "CCDC178 was reported to be mutated in hepatocellular carcinoma and gastric carcinoma." (PMID 34540650, 2021). "The coiled-coil domain-containing protein 178 (CCDC178), a member of the coiled-coil domain-containing protein family, is aberrantly expressed in hepatocellular carcinoma and gastric cancer." (PMID 35780460, 2023).
hepatocellular carcinoma (4 papers, 2020 to 2023). A malignant tumor that arises from hepatocytes. "CCDC178 was mutated in 3 samples of BMs: it was shown to be associated with the development of metastases from hepatocellular carcinoma, the regulation of the ERK pathway and anoikis resistance." (PMID 33400739, 2020). "CCDC178 deficiency impaired the ERK activation in hepatocellular carcinoma." (PMID 34540650, 2021). "The coiled-coil domain-containing protein 178 (CCDC178) has been found to be mutated in hepatocellular carcinoma (HCC) and GC cells, and it was found to promote HCC metastasis by mediating anoikis." (PMID 36059494, 2022). "A previous study showed that CCDC178 facilitates the metastasis of hepatocellular carcinoma cells via ERK/MAPK signaling." (PMID 35780460, 2023).
colon carcinoma (1 paper, 2024). "For instance, the expression of ANKRD6 and ITIH3 was associated with reduced OS in colon carcinoma (COAD) and kidney renal papillary cell carcinoma (KIRP), and the expression of CCDC178 in bladder urothelial carcinoma (BLCA) and thyroid carcinoma (THCA)." (PMID 38480611, 2024).
gastric adenocarcinoma (1 paper, 2021). "In our study, CCDC178 mutations were significantly associated with a poor survival outcome in gastric adenocarcinoma." (PMID 34540650, 2021). "Combining Kaplan–Meier survival analysis log-rank p-value, mutation coexistence pattern, and the result of random survival forest algorithm, we selected UTRN, MUC16, CCDC178, and HYDIN as candidates for an accurate prediction of survival in gastric adenocarcinoma patients." (PMID 34540650, 2021).
male infertility (1 paper, 2024). The inability of the male to effect fertilization of an ovum after a specified period of unprotected intercourse. "Ccdc178 knockout resulted in complete male infertility, and their testes were smaller than those of Ccdc178+/+ mice." (PMID 39157459, 2024). "In conclusion, CCDC178 is predominantly expressed in the testis and its knockout results in male infertility with an oligoasthenospermia-like phenotype." (PMID 39157459, 2024). "Although no human CCDC178 mutations have been linked to male infertility yet, our studies strongly suggest a potential association of CCDC178 mutations with the pathogenesis of oligoasthenospermia or multiple morphological abnormalities of the flagella in some patients." (PMID 39157459, 2024).
myopia (1 paper, 2023). "Additionally, we identified 4 significant DEGs of myopia: KIAA1211, CALR3, DNASE2B, and CCDC178, and 2 common targets: AR and TYRO3 among DZP, myopia, DEG analysis, and WGCNA." (PMID 37747014, 2023).
oligospermia (1 paper, 2024). Decreased number of spermatozoa in the semen. "Different from Cfap53 knockout, Ccdc178 knockout not only leads to a phenotype like multiple morphological abnormalities of the flagella but also results in severe oligospermia in mice, suggesting that CCDC178 may also be involved in spermiation." (PMID 39157459, 2024).
rheumatoid arthritis (1 paper, 2023). A chronic, systemic autoimmune disorder characterized by inflammation in the synovial membranes and articular surfaces. "Notably, cg26878734 (LNPK) was previously associated with rheumatoid arthritis in a monozygotic twin study, suggesting its involvement in inflammation, while genetic variability at the CCDC178 gene has been associated with body fat distribution in a genome-wide association study." (PMID 37393279, 2023).
cancer (4 papers, 2015 to 2021). A tumor composed of atypical neoplastic, often pleomorphic cells that invade other tissues. "However, the depletion of CCDC178 inhibited ERK activation, which underlies the role of CCDC178 as a protein oncogene involved in anoikis resistance and cancer metastasis; therefore, identifying the potential of targeting this polypeptide in cancer treatment." (PMID 33854965, 2021). "The relative transcriptional level of CCDC178 was significantly downregulated in several types of carcinoma compared with adjacent non-cancerous tissues in TCGA cohorts." (PMID 34540650, 2021).
tumor (3 papers, 2017 to 2024). "These genes are ANKRD6, ITIH3, SORCS3, NPY1R and CCDC178, which form a signature associated to adverse clinic-pathological features such as advanced tumor stage, poor prognosis and disease recurrence in GC." (PMID 38480611, 2024).
CCDC178 also shares sentences with these, for which no sentence is quoted: chronic gastritis (1 paper); metastatic cancer (1); ovarian tumor (1); thyroid carcinoma (1).